MCM2 (minichromosome maintenance complex component 2)
Diseases named in the same sentence as MCM2 in open-access papers (continued):
Sharing a sentence is not in itself a finding about the gene and the disease.
medulloblastoma (7 papers, 2014 to 2021). A malignant, invasive embryonal neoplasm arising from the cerebellum. "During the medulloblastoma tumorigenesis process, genetic or epigenetic inactivating mechanisms cause a shutdown of miR-31 expression, which leads to an enhanced expression of its downstream target gene MCM2." (PMID 24970811, 2014). "Global gene expression profiling of mouse medulloblastomas and bioinformatics analyses of microRNA targets suggest that minichromosome maintenance complex component 2 (MCM2) is a likely target gene of miR-31 in suppressing cell growth." (PMID 24970811, 2014). "In our earlier study, we demonstrated that knockdown of MCM2 significantly inhibited the cell growth, migration, and invasion in medulloblastoma." (PMID 25098679, 2014). "Taken together, these data indicate that miR-31 suppresses medulloblastoma tumorigenesis by negatively regulating DNA replication via MCM2." (PMID 24970811, 2014). "MCM2 is also a target gene of miR-31 in suppressing medulloblastoma cell growth." (PMID 27780919, 2016). "The overexpression of MCM2 and MCM3 increased the proliferation and migration of medulloblastoma." (PMID 28460433, 2017).
lymphoma (6 papers, 2005 to 2025). A malignant (clonal) proliferation of B- lymphocytes or T- lymphocytes which involves the lymph nodes, bone marrow and/or extranodal sites. "Mice with reduced expression of MCM2 due to an MCM2 mutant allele die with lymphoma within the first few months after birth." (PMID 39929806, 2025). "Early studies have shown that the Mcm4(D573H) allele destabilizes the MCM2–7 complex, resulting in chromosome instability and the formation of spontaneous T cell lymphoblastic leukemia/lymphoma (T-ALL)." (PMID 39929806, 2025). "Lastly, mice deficient for MCM2 (a component of the Pre-RC) develop lymphomas and exhibit elevated levels of DSBs at the 45S rDNA repeats in their genomes." (PMID 29036220, 2017). "Although these mice develop normally, MCM2-deficiency results in stem cell deficiencies in multiple tissues, and ultimately, cancer, primarily lymphomas." (PMID 28915237, 2017). "Subsequently, it was reported that mice containing 1/3 the normal level of MCM2 succumbed to lymphomas at a very young age, and had diverse stem cell proliferation defects." (PMID 20838603, 2010). "MCM2 was initially detected from lymphoma cells and, thus, has a tumor origin." (PMID 35003254, 2021). "Mice with ∼35% of WT MCM2 protein, but not 62%, showed early latency (10–12 week) lymphoma susceptibility." (PMID 20838603, 2010). "Analysis of MCM proteins by means of immunohistochemistry has been shown to be of prognostic value in a diverse range of human malignancies; in lymphoma however, high expression of Mcm2 has been described in DLBCL, but so far data have never been evaluated with respect to clinical outcome." (PMID 16368013, 2005).
meningioma (6 papers, 2013 to 2025). A generally slow growing tumor attached to the dura mater. "Recently, the immunohistochemistry (IHC) markers S100B, SCGN, ACADL and MCM2 have been shown to be associated with underlying biological subtypes of meningioma (MG1-MG4)." (PMID 36685704, 2023). "In meningiomas high Mcm2 PI was associated with early recurrence." (PMID 23618321, 2013). "MCM2 + meningiomas displayed more frequent atypical features (prominent nucleoli, small cells with high nuclear-to-cytoplasmic ratio) and CDKN2A hemizygous deletion (HeDe) (P = 0.011)." (PMID 37014425, 2023). "In accordance with the reported frequent inactivation of tumor suppressor genes in MG4 and MG3, atypical meningiomas with MCM2 or ACADL immunostaining had higher mitotic counts, reflecting a high proliferative activity." (PMID 37014425, 2023). "Deregulation of MCM2–7 can be potential biomarkers in meningioma tumor tissues.Consistent with the previous findings, our present work observed deregulations of MCM1–10 genes in LUAD cancer tissues which can be serve as potential diagnostic biomarkers." (PMID 31323040, 2019). "Twelve meningiomas were classified as IHC-G1 (MCM2-/ACADL-)." (PMID 37014425, 2023). "Finally, 34 meningiomas, showing MCM2 immunostaining in 20–90% cells, were IHC-G3 (MCM2 +); 17 of these cases had concurrent ACADL immunostaining in 10–80% tumor cells." (PMID 37014425, 2023). "In this study, we analyzed for the first time whether ACADL and MCM2 immunostainings, used as surrogates to determine molecular groups MG3 and MG4, could predict the recurrence risk of atypical meningiomas and to identify cases which could benefit from adjuvant treatments in clinical practice." (PMID 37014425, 2023). "MG3 and MG4 may be recognized using immunohistochemistry against ACADL and MCM2, but whether these immunostainings may be useful to identify meningiomas with a higher recurrence risk has not been investigated." (PMID 37014425, 2023). "In total, 244 patients with meningiomas with tissue in TMAs were included and the IHC markers S100B, SCGN, ACADL and MCM2 were analyzed." (PMID 36685704, 2023). "In conclusion, this is the first study to show that immunostainings for MCM2 and ACADL may be useful for identifying atypical meningiomas characterized by higher genomic instability, CDKN2A HeDe, higher integrated molecular grade, recurrence risk, and shorter RFS." (PMID 37014425, 2023). "In this study, we investigated whether the immuno-expression of ACADL and MCM2, used as surrogates of molecular groups MGM3 and MGM4, is associated with reduced RFS or with clinical, pathological and genetic features in a cohort of 55 atypical meningiomas treated with surgery and no radiotherapy." (PMID 37014425, 2023). "All four meningiomas lacking MCM2 and ACADL immunostaining (IHC-G1) were classified as integrated grade 1; all three meningiomas in IHC-G2 (ACADL + /MCM2-) were classified as integrated grade 3, whereas 5/8 tumors in IHC-G3 (MCM2 +) were classified as integrated grade 2 or 3 (P = 0.0166)." (PMID 37014425, 2023).
osteosarcoma (6 papers, 2012 to 2023). A usually aggressive malignant bone-forming mesenchymal neoplasm, predominantly affecting adolescents and young adults. "To date, the role and underlying mechanism of MCM2 and MCM3 involved in osteosarcoma remain largely unclear." (PMID 28460433, 2017). "In order to determine the underlying mechanism by which MCM2 and MCM3 promote osteosarcoma, co-immunoprecipitation was performed in 293T cells." (PMID 28460433, 2017). "Taken together, these results suggest that the MCM2/MCM3–DHX9 axis has an important role in osteosarcoma progression." (PMID 28460433, 2017). "Taken together, MCM2 and MCM3 promote osteosarcoma progression via associations with DHX9 and thus are potential therapeutic targets for patients with osteosarcoma." (PMID 28460433, 2017). "Taken together, MCM2 and MCM3 were correlated with DHX9 in tumor samples and were associated with poor prognosis in osteosarcoma patients." (PMID 28460433, 2017). "This study, for the first time, demonstrates the interactions of MCM2/MCM3 with DHX9 in osteosarcoma cells." (PMID 28460433, 2017). "The results showed that knockdown of MCM2 or MCM3 inhibited osteosarcoma cell proliferation in MNNG/HOS cells, suggesting that they played important roles in the tumorigenesis of osteosarcoma." (PMID 28460433, 2017). "In the present study, the co-immunoprecipitation technique was used to explore the underlying mechanism by which MCM2 and MCM3 influence osteosarcoma." (PMID 28460433, 2017). "The data revealed that the knockdown of MCM2 or MCM3 significantly inhibited the growth of osteosarcoma cells." (PMID 28460433, 2017). "Collectively, knockdown of MCM2 or MCM3 dramatically inhibits osteosarcoma cell growth in vitro and in vivo." (PMID 28460433, 2017). "Further validation showed that high MCM2 and MCM3 expression levels in osteosarcoma were associated with a poor prognosis." (PMID 28460433, 2017). "The results of this study demonstrated that knockdown of MCM2 or MCM3 inhibited osteosarcoma cell growth in vitro and in vivo." (PMID 28460433, 2017). "(2017) identified proteins minichromosome maintenance protein 2 (MCM2) and minichromosome maintenance protein 3 (MCM3) through MS analysis of osteosarcoma cell lines and demonstrated an association of positive IHC expression with inferior tumor free- and overall- survival in 129 tissue samples." (PMID 37197427, 2023). "Taken together, these results indicated that MCM2 or MCM3 knockdown could hinder the tumorigenesis of osteosarcoma cells in vivo." (PMID 28460433, 2017). "Here, we show that knockdown of MCM2 or MCM3 inhibits osteosarcoma growth in vitro and in vivo." (PMID 28460433, 2017). "More importantly, this report provides, for the first time, experimental evidence for interactions of MCM2 and MCM3 with DHX9 in osteosarcoma cells and the importance of these interactions, clarifying the molecular mechanisms of MCM2 or MCM3-mediated tumorigenesis." (PMID 28460433, 2017). "Our data demonstrated that knockdown of MCM2 or MCM3 inhibited osteosarcoma cell proliferation." (PMID 28460433, 2017). "In sum, we hypothesized that MCM2 and MCM3 were associated with the proliferation of osteosarcoma cells." (PMID 28460433, 2017). "Notably, MCM2 and MCM3 expression levels were positively correlated with the DHX9 expression level in tumor samples and were associated with a poor prognosis in patients with osteosarcoma." (PMID 28460433, 2017). "Thus, MCM2 and MCM3 are associated with DHX9 in osteosarcoma cells." (PMID 28460433, 2017). "However, the role of DHX9 in osteosarcoma and whether MCM2 and MCM3 function via DHX9 are largely unknown." (PMID 28460433, 2017). "Functional screening was conducted on nine chosen proteins and inhibition of proteins MCM2 and MCM3 were found to reduce osteosarcoma cell proliferation." (PMID 37197427, 2023). "A positive correlation between MCM2 or MCM3 and DHX9 expression was detected in osteosarcoma tissues." (PMID 28460433, 2017).
osteosarcoma (continued). "To assess interactions between proteins, we pulled down MCM2 or MCM3 and probed their interactions with other proteins in 293T cells and osteosarcoma cells." (PMID 28460433, 2017). "The overexpression of DHX9 rescued the MCM2 and MCM3 knockdown-induced osteosarcoma growth inhibition, showing that the control of cell proliferation by MCM2 and MCM3 was largely dependent on DHX9." (PMID 28460433, 2017). "In co-immunoprecipitation and co-localization experiments, MCM2 and MCM3 were found to interact with DExH-box helicase 9 (DHX9) in osteosarcoma cells." (PMID 28460433, 2017). "Overexpression of DHX9 rescued the MCM2 and MCM3 knockdown-induced osteosarcoma growth inhibition by regulating numerous biological processes." (PMID 28460433, 2017). "By functional screening, minichromosome maintenance protein 2 (MCM2) and minichromosome maintenance protein 3 (MCM3) were found to be related to osteosarcoma cell growth." (PMID 28460433, 2017). "Collectively, these results reveal that knockdown of MCM2 or MCM3 inhibits osteosarcoma cell proliferation via DHX9 and DHX9 plays an oncogenic role in osteosarcoma." (PMID 28460433, 2017). "By functional screening, MCM2 and MCM3, components of the MCM2-7 complex, were found to be related to osteosarcoma proliferation." (PMID 28460433, 2017). "Further analysis indicated that MCM2 and MCM3 levels were positively correlated with recurrence (P = 0.000), indicating that MCM2 and MCM3 play important roles in osteosarcoma recurrence." (PMID 28460433, 2017). "A Spearman correlation analysis revealed a significant correlation between the expression levels of MCM2 and DHX9 (R = 0.195, P = 0.027), as well as between the levels of MCM3 and DHX9 (R = 0.248, P = 0.005) in osteosarcoma tissues." (PMID 28460433, 2017). "A rescue study showed that the decreased growth of osteosarcoma cells by MCM2 or MCM3 knockdown was reversed by DHX9 overexpression, indicating that MCM2 and MCM3 activity was DHX9-dependent." (PMID 28460433, 2017). "To further determine the clinicopathological significance of MCM2 and MCM3 in osteosarcoma, we performed an immunohistochemical (IHC) analysis of MCM2 and MCM3 using a tissue microarray that included an independent set of 129 cases of osteosarcoma." (PMID 28460433, 2017). "For instance, AURKA, MCM2 and CCNB2 which are among the prototypical genes showing overexpression in the most aggressive osteosarcomas were among the genes that were significantly reduced in OS cells treated with 5-AzadC and 4-PBA." (PMID 22957032, 2012). "Knockdown of MCM2 and MCM3 significantly inhibited osteosarcoma growth in vitro and in vitro." (PMID 37197427, 2023). "Notably, we found that MCM2 and MCM3 were independent prognostic factors for tumor-free survival (TFS) and overall survival (OS) in patients with osteosarcoma." (PMID 28460433, 2017). "However, the functions and molecular mechanisms of MCM2 and MCM3 in osteosarcoma are still far from fully understood." (PMID 28460433, 2017). "MCM2 and MCM3 were found to interact and co-localize with DHX9 in osteosarcoma." (PMID 28460433, 2017). "MCM2 and MCM3 may be sensitive biomarkers to predict prognosis for osteosarcoma patients." (PMID 28460433, 2017). "In addition, positive correlations between both MCM2 and MCM3 and DHX9 were found in osteosarcoma." (PMID 28460433, 2017). "Therefore, intervention targeting the MCM2/3–DHX9 axis may be a feasible and effective strategy for the treatment of osteosarcoma." (PMID 28460433, 2017).
squamous intraepithelial lesion (6 papers, 2007 to 2025). "A few have reported role of ProExC with Topoisomerase II alpha (TOP2A) and minichromosome maintenance protein 2 (MCM2) in detection of cervical high-grade squamous intraepithelial lesions from cytologic samples." (PMID 17374161, 2007). "In another study, Kaur and colleagues reported that the expression level of MCM2 was upregulated with increasing fold change during the progression from the low-grade squamous intraepithelial lesion to the high-grade squamous intraepithelial lesion and the highest in SCC." (PMID 37746664, 2023).
cervical dysplasia (5 papers, 2008 to 2023). "Along with to p16INK4a, other cellular biomarkers such as Ki67, MCM2, Topo2α, and hTERT have been described as potential markers for cervical dysplasia detection, triage, and diagnosis." (PMID 36980443, 2023). "A recent immunohistochemical study has shown that MCM2 is differentially expressed in normal epithelium compared to high grade cervical intraepithelial neoplasia (CIN) and invasive cancer." (PMID 23874974, 2013). "Therefore the AUC of 0.78 found on the present study suggests that MCM-2 is a borderline biomarker in diagnosing high grade cervical dysplasia and invasive tumors." (PMID 22493662, 2012). "Similar difference in the protein levels of CDC6 and MCM2 was observed in cervical dysplasia." (PMID 19116018, 2008).
glioblastoma (5 papers, 2014 to 2022). The most malignant astrocytic tumor (WHO grade IV). "To answer this hypothesis, we reproduced the peri-necrotic niche in vitro with T98G glioblastoma cells and determined the protein expression profiles of GINS components as well as MCM2, one of the associate molecules of GINS, in T98G cells." (PMID 30465075, 2019). "Furthermore, MCM2 is highly expressed in CSCs of retinoblastoma and glioblastoma." (PMID 26430873, 2015).
lymph node metastasis (5 papers, 2005 to 2021). "Among these factors, lymph node metastasis, recurrence, and MCM2 localization correlated with overall survival, as determined by univariate analysis." (PMID 29963273, 2018). "Further study with large sample size is required to clarify the correlation between maspin and MCM2 expression and lymph node metastasis." (PMID 21943228, 2011). "The present study aimed to evaluate the expression of maspin and MCM2 in salivary gland carcinomas and their value to predict lymph node metastasis." (PMID 21943228, 2011). "A logistic regression model shows that none of the markers including Ki67, Mcm2, geminin, ER, PR, HER-2, nor the Mcm2/Ki67 or geminin/Ki67 ratios, have any statistically significant association with lymph node metastasis." (PMID 16278669, 2005). "Subcellular localization of MCM2 in clear cell carcinoma did not significantly correlate with clinico-pathological factors such as age, FIGO stage, TNM stage, tumor size, lymph node metastasis, and recurrence." (PMID 29963273, 2018).
neuroblastoma (5 papers, 2020 to 2023). Neuroblastoma (NB) is the most common solid, extracranial childhood tumor. "We analyzed samples obtained from patients with neuroblastoma, revealing that higher levels of MCM2 and MCM10 mRNA were associated with poor survival rate." (PMID 35056094, 2021). "BI-2536 may exert multiple effects on neuroblastoma cell death through inhibition of MCM2 and MCM10." (PMID 35056094, 2021). "The survival rates were not significantly changed in patients with high or low expression of MCM2 or MCM10 with MYCN-amplified neuroblastoma, suggesting that MYCN amplification is more dominant than MCM expression in determining poor prognosis in this patient subgroup." (PMID 35056094, 2021). "The mRNA content was determined using several multiplex droplet digital PCR (ddPCR) assays for a neuroblastoma-specific gene panel (PHOX2B, TH, CHRNA3) and a cell cycle regulation panel (E2F1, CDC6, ATAD2, H2AFZ, MCM2, DHFR)." (PMID 37046768, 2023). "For neuroblastoma, it is known that MYCN amplification is a feature of aggressive disease and that this in turn can upregulate E2F1 and MCM2." (PMID 37046768, 2023). "Therefore, these experiments confirm the dependence of MCM2 and MCM10 in neuroblastoma cells, and can be cellular targets for the development of drug therapy." (PMID 35056094, 2021). "MCM10, MCM2, MCM3, and MCM6 are among the high-risk signature correlating with poor prognosis in both MYCN-amplified and MYCN-non-amplified neuroblastoma." (PMID 35056094, 2021).
oligodendroglioma (5 papers, 2004 to 2014). A well-differentiated (WHO grade II), diffusely infiltrating neuroglial tumor, typically located in the cerebral hemispheres. "In our study Mcm2 PIs were lower than Ki67/MIB-1 PIs and comparable with those in pilocytic astrocytomas, whereas in oligodendrogliomas the Mcm2 indices were higher." (PMID 23618321, 2013). "As an example, in a study on oligodendrogliomas Mcm2 proliferative index (PI) showed good correlation with mitotic index, Ki67/MIB-1 PI, and survival." (PMID 23618321, 2013). "Values for Mcm2 obtained in this study showed a pattern of increasing expression with grade similar to that observed previously by us in a separate series of oligodendroglial tumours." (PMID 15199392, 2004). "Here we investigate the regulation of Ki67, Mcm2, p21, caspase 3 and Geminin in a series of 55 oligodendrogliomas to provide an integrated picture of how cellular proliferation and programmed cell death are dysregulated in these tumours." (PMID 15199392, 2004). "Here we investigate the regulation of DNA replication-licensing factors Mcm2 and Geminin in a series of oligodendrogliomas to examine the potential linkages between aberrant Geminin expression and tumour progression." (PMID 15199392, 2004).
renal cell carcinoma (5 papers, 2005 to 2022). "On the other hand, only a handful of studies have been previously carried out on the expression of MCM-2 in renal cell carcinoma." (PMID 27532114, 2016). "In this study we have shown that IHC expression of Ki-67 and MCM-2 not only correlates with the Fuhrman nuclear grade but is more objective and reproducible and can be used in conjunction with Fuhrman nuclear grade to determine prognosis in renal cell carcinoma." (PMID 27532114, 2016).